CBLL2 (Cbl proto-oncogene like 2)
Description:
E3 ubiquitin ligase catalyzing the covalent attachment of ubiquitin moieties onto substrate proteins. May operate on tyrosine-phosphorylated SRC substrates.
Synonyms: ZNF645; FLJ25735; HAKAIL; CT138
Tractability: PROTAC: ubiquitination databases record sites on it.
Gene: Protein-coding gene on chromosome X (22,272,913 to 22,274,461, forward strand). Ensembl gene ENSG00000175809.
Subcellular location: Cytoplasm
Pathways (Reactome):
Immune System: Antigen processing: Ubiquitination & Proteasome degradation
Gene Ontology:
Molecular function: protein binding; ubiquitin protein ligase activity
Biological process: protein ubiquitination; regulation of cell adhesion
Cellular component: cytoplasm; nucleus; RNA N6-methyladenosine methyltransferase complex
Homologues: Orthologues: chimpanzee CBLL2 (96% identical), macaque CBLL2 (85% identical), tropical clawed frog cbll1 (47% identical), zebrafish cbll1 (39% identical), Drosophila melanogaster Hakai (21% identical). Paralogues in human: CBLL1 (51% identical).
Diseases named in the same sentence as CBLL2 in open-access papers:
CBLL2 is named in the same sentence as 1 disease in open-access papers, as found by Europe PMC text mining. Sharing a sentence is not in itself a finding about the gene and the disease.
CBLL2 shares sentences with these, for which no sentence is quoted: cancer (1 paper).